HPSE (heparanase)
Diseases named in the same sentence as HPSE in open-access papers (continued):
Sharing a sentence is not in itself a finding about the gene and the disease.
tumor (continued). "By cleaving heparan sulfate on the surface of NK cells, heparanase secreted by tumors can increase levels of soluble heparan sulfate, and consequently inhibit NK cell activity and cytotoxicity against tumor cells." (PMID 31110966, 2019). "Enzymatic activity of heparanase degrading specifically HS chains of HSPG is involved in tumor progression and metastasis." (PMID 30237860, 2018). "Cleavage of HS by heparanase leads to disassembly of the ECM, thereby promoting cell dissemination associated with tumor metastasis, angiogenesis and inflammation." (PMID 30627323, 2018). "The degradation of HS by heparanase regulates the bioavailability of HS-binding proteins, primes the tumour microenvironment and facilitates the spread of invasive tumour and inflammatory cells." (PMID 30441818, 2018). "Heparanase regulates numerous biological processes that drive tumour growth, metastasis and angiogenesis." (PMID 30441818, 2018). "Several lines of evidence indicate that tumor sensitivity to drug treatment can be affected by altered expression of cell-surface HSPGs and/or heparanase." (PMID 30413079, 2018). "In fact, a large body of evidence indicates that the altered expression or activity of either heparanase or endosulfatases determines a profound impact on tumor behavior." (PMID 30413079, 2018). "Heparanase (HPSE), a heparan sulfate-specific endo-β-D-glucuronidase, plays an important role in tumor cell metastasis through the degradation of extracellular matrix heparan sulfate proteoglycans." (PMID 30333909, 2018). "Further studies suggested a role for heparanase overexpression in tumor protection against radiotherapy." (PMID 30413079, 2018). "High levels of HPSE have been detected in many malignancies and tissues, where it is involved in tumor cell growth, angiogenesis, tumor invasion, and metastasis by degrading and remodeling the ECM." (PMID 29849826, 2018). "Heparanase, the sole heparan sulfate (HS) degrading endoglycosidase, regulates multiple biological activities that enhance tumor growth, metastasis, angiogenesis, and inflammation." (PMID 29721203, 2018). "More recent studies provided compelling evidence that tie heparanase levels with all steps of tumor formation including tumor initiation, growth, metastasis, and chemoresistance." (PMID 29464068, 2018). "Our results add heparanase to the growing list of proteins that are differentially expressed by the primary tumor and its metastases." (PMID 29464068, 2018). "This notion is reinforced by preclinical studies revealing a marked inhibition of tumor growth in mice treated with heparanase-inhibitors (i.e., roneparstat, pixatimod) and neutralizing antibodies." (PMID 30627323, 2018). "This notion is reinforced by preclinical studies revealing a marked inhibition of tumor growth in mice treated with heparanase-inhibitors, now in phase I/II clinical trials in cancer patients." (PMID 29464068, 2018). "In these PDXs, PG545 not only inhibited tumor growth but also practically prevented tumor metastasis, thus clearly supporting the pro-metastatic function of the heparanase enzyme." (PMID 29721203, 2018). "Through this co-operation, heparanase and syndecan-1 control tumor cell growth, adhesion, spread, and signaling at a distance through exosomes." (PMID 30413079, 2018). "Strategies to attenuate heparanase effects by heparin mimetics or peptides interrupting the TF–heparanase interaction are good candidates to attenuate tumor growth and thrombotic manifestations." (PMID 30180930, 2018). "Compelling evidence ties heparanase levels with all steps of tumor formation including tumor initiation, growth, metastasis, and chemoresistance." (PMID 30627323, 2018). "In other cases, however, we found that heparanase staining is changed significantly in the primary tumor vs its metastasis, in both ways." (PMID 29464068, 2018).
tumor (continued). "HPSE, the only known endogenous β-glucuronidase in mammals, has been shown to be positively connected with tumor cell invasion and metastasis." (PMID 29849826, 2018). "High expression of HPSE mRNA and protein was found in the tumor and in ascites of SRCA as well as in KATO-III cell line." (PMID 30333909, 2018). "In response to paclitaxel in mouse models, tumor-infiltrating macrophages secrete cathepsin, which activates heparanase." (PMID 29527513, 2018). "Numerous clinical studies have consistently demonstrated that upregulation of heparanase expression correlates with increased tumor size, tumor angiogenesis, enhanced metastasis and poor prognosis." (PMID 29721203, 2018). "In contrast, knockdown of heparanase or treatment of tumor-bearing mice with heparanase-inhibiting compounds, markedly attenuated tumor progression, further underscoring the potential of anti-heparanase therapy for multiple types of cancer." (PMID 29721203, 2018). "The HS endo‐glucuronidase (heparanase) is overexpressed in most tumor tissues, correlating with tumor vascular density and metastatic potential, and with patient survival." (PMID 28286736, 2017). "Human heparanase is an endoglucuronidase that cleaves heparan sulfate chains thereby regulating multiple biological activities that together enhance tumor growth, metastasis and angiogenesis." (PMID 28359266, 2017). "Heparanase is an endoglycosidase which cleaves the HS side chains of heparan sulfate proteoglycans (HSPG) in the ECM surrounding tumor cells." (PMID 28974047, 2017). "Given that heparanase expression promotes tumor growth in most cancers, this finding highlights a crosstalk between heparanase, HS, and TGF‐β1 function in tumorigenesis." (PMID 28286736, 2017). "There are some natural substances, including arctigenin, matrine, and NAX014 (a synthetic derivative 13-(4-chlorophenylethyl) berberine iodide) that decrease heparanase expression, which are partly responsible for its anti-tumor and anti-metastatic activity." (PMID 28505136, 2017). "Heparanase is overexpressed by tumor cells and degrades the extracellular matrix proteoglycans through cleavage of heparan sulfates (HS), allowing pro-angiogenic factor release and thus playing a key role in tumor angiogenesis and metastasis." (PMID 28486399, 2017). "Together, these and other results critically support the intimate involvement of heparanase in tumor progression and encourage the development of heparanase inhibitors as anti-cancer therapeutics." (PMID 28359266, 2017). "Some evidence also suggests that high HPSE expression is correlated with increases in tumor cell metastasis and poor prognosis." (PMID 28388549, 2017). "The fractionated polysaccharides were then tested in a heparanase-rich medium-based in vitro model, mimicking tumor microenvironment, to determine their effect on microvascular endothelial cells (HSkMEC) angiogenesis." (PMID 28486399, 2017). "For example, HPSE inhibitors dramatically inhibited cell invasion and reduced tumor growth in animal models." (PMID 28388549, 2017). "Among them, heparanase, an endo-β-d-glucuronidase, plays a crucial role in tumor development, metastasis and angiogenesis." (PMID 28486399, 2017). "In the experimental models of HPSE transgenic and knockout mice, the activation of heparanase changes the microenvironment of tumour and positively correlates with its development, while the suppression of heparanase reduces the amount of tumour cells." (PMID 29104277, 2017). "The heparan sulfate endoglycosidase heparanase (HPSE) is involved in tumor growth, chronic inflammation and fibrosis." (PMID 29097791, 2017). "HPSE is commonly upregulated in cancer cells to impact angiogenesis, metastasis, tumor growth and inflammation." (PMID 28969075, 2017). "The anti-tumor activity of GYII and its decomposed recipes is, at least partly, associated with decreased heparanase and growth factor expression, which subsequently suppressed the activation of the ERK and AKT pathways." (PMID 28505136, 2017).
tumor (continued). "At the same time, the growth of experimental tumoursin vivo depends on the level of ectopic expression of heparanase; a moderate level of expression enhanced tumour growth, while a high level suppressed it." (PMID 29104277, 2017). "Heparanase (HPSE) expression was identified in 50% of GBM tumours by immunostaining, and was characterised by a high intratumoural heterogeneity of the presence of the HPSE protein." (PMID 29104277, 2017). "The exposition of HSkMEC cells cultured in MatrigelTM to tumor microenvironment conditions such as hypoxia or nutrient deprivation was studied regarding the angiogenesis behavior and heparanase production." (PMID 28486399, 2017). "Heparanase is a heparan sulfate degrading enzyme that cleaves heparan sulfate (HS) on the HS proteoglycans (HSPG) and has been implicated in tumor metastasis and inflammation." (PMID 28720149, 2017). "Mechanistic studies revealed that circHIPK3 abundantly sponged miR-558 and suppressed heparanase (HPSE) expression, which is involved in regulating tumor invasion and metastasis." (PMID 29349062, 2017). "This is based on compelling evidence that tie heparanase with tumor initiation, progression, metastasis, and chemo-resistance." (PMID 27732945, 2016). "In summary, our data provide new insight into heparanase mechanism of action in cancer and reveal the potential of anti-heparanase therapy to enhance response to chemotherapy and to prevent tumor relapse, thus improving patient outcome." (PMID 26624982, 2016). "Remodeling of the EGL and ECM by heparanase is important for various physiological and pathological processes, including inflammation, wound healing, tumor angiogenesis, and metastasis." (PMID 27416066, 2016). "This is consistent with the well-established roles for heparanase in driving inflammation and the progression of different tumor types." (PMID 26624982, 2016). "Previous studies have primarily focused on the functions of platelet heparanase in association with degradation of ECM heparan sulfate (HS), consequently, facilitating extravasation of blood-born leukocytes and tumor cells." (PMID 27129145, 2016). "HPSE is an enzyme highly expressed in aggressive MM cells and that we and others have shown is a key promoter of MM progression via the remodeling of the tumor microenvironment." (PMID 26849235, 2016). "To fully understand the role of hTERT in tumor metastasis, we sought to focus on the effect of hTERT on heparanase expression that is an important endogenous endoglycosidase degrading extracellular matrix in the present study." (PMID 26689987, 2016). "This confirms and significantly expands previous report and suggests that heparanase not only enhances the dissemination of tumor cells but also promotes the growth/aggressiveness of established lesions." (PMID 27732945, 2016). "Enhanced heparanase expression in tumour cells stimulates exosome biogenesis, alters exosome protein composition, and enhances the ability of exosomes to promote tumour cell spreading and endothelial cell migration." (PMID 27408707, 2016). "HS mimics, synthesized and selected as heparanase inhibitors, have shown anti-tumor efficacy as well as antiangiogenic and antimetastatic properties, in preclinical studies leading a few of them to clinical evaluation." (PMID 27374103, 2016). "A potential role of heparanase in coagulation has also been suggested based on the high expression of this protein during the pro-thrombotic state of most neoplasms." (PMID 27322195, 2016). "It has also been documented that HPSE is functionally related to the invasion and metastasis of tumor cells." (PMID 27595937, 2016). "Heparanase, an endo-β-D-glucuronidase, is involved with tumor angiogenesis and metastasis via the regulation of heparan sulfate (HS) cleavage in several cancers." (PMID 25669977, 2015). "Logistic regression analysis showed that increased heparanase-1 and heparanase-2 expression was exclusively dependent on the tumor." (PMID 25351637, 2015).
tumor (continued). "Heparanase is a centrally important regulator of metastases, tumor microenvironment interactions, and bone metabolism via actions on many targets." (PMID 25944690, 2015). "High expression of heparanase-1 was also noted in other tissues like lung, lymph node and liver, as well as in the stromal tumor tissues." (PMID 25351637, 2015). "Based on above findings and analysis, we conclude that HPSE not only plays an important role in tumor invasion and migration, but also contributes to the adhesion of HCC cells." (PMID 26839882, 2015). "Increased expression of heparanase in various tumours correlates with tumour invasiveness, angiogenesis and poor prospective survival." (PMID 26039697, 2015). "Heparanase (HPSE) is an endo-beta-glucoronidase implicated in the process of tumor invasion, and the heparanase-2 (HPSE2) modulates HPSE activity." (PMID 26488476, 2015). "For this reason, the CD138/heparanase axis is consistently gaining attention as therapeutic target due to its importance in driving cancer and in determining tumor aggressiveness." (PMID 26025441, 2015). "Mast cells, along with tumor infiltrating neutrophils, endothelial cells, and macrophages exhibit heparanase activity." (PMID 25734659, 2015). "As the enzyme primarily responsible for the degradation of HS chains, heparanase has been shown to modify tumor cell responses to HS-binding of Wnt3a such as effects on cell proliferation and adhesion, in addition to its HS-chain degrading activity." (PMID 25669977, 2015). "In MM:bone cocultures, it decreased tumor RANKL, increased osteoblastic activity (type 1 collagen) and decreased osteocyte FGF23 - which in turn should decrease tumor heparanase." (PMID 25944690, 2015). "For example, circulating tumor cells that metastasize to the brain overexpress proteins such as heparanase (HPSE) that allow cancer cells to interact with brain vasculature." (PMID 25926557, 2015). "Inflammatory cell migration to the lung has a number of similarities with tumour cell metastasis, for example, secreting heparanase to degrade ECM structure." (PMID 26039697, 2015). "It has been shown that heparanase is highly expressed with a positive correlation with tumour stage and poor prognosis in RCC." (PMID 26482227, 2015). "Heparanase upregulation of tumor tissues, blood, or urine have been correlated with increased lymph node and distant metastasis and with shorter postoperative survival of cancer patients." (PMID 26569485, 2015). "It has been demonstrated that heparanase of tumor tissues was upregulated in 70% of malignant salivary tumors and was inversely correlated with cumulative survival and disease-free survival." (PMID 26569485, 2015). "High levels of HPSE mRNA and protein are expressed in most malignant tumors including HCC and are closely associated with tumor metastasis, angiogenesis, and other diverse pathological processes." (PMID 26839882, 2015). "A análise feita por regressão logística mostra que aumento na expressão de heparanase-1 e heparanase-2 é exclusivamente dependente da presença de tumor." (PMID 25351637, 2015). "A number of studies have found high levels of heparanase in tumor cells in comparison to normal and pre-cancerous cells." (PMID 24887057, 2014). "Both over-expression and silencing of the heparanase gene indicate that heparanase enhances cell dissemination and promotes the establishment of a vascular network that accelerates primary tumor growth and metastasis." (PMID 24465803, 2014). "And fourthly, heparanase is involved in exosome formation by cancer cells, which has recently been shown to promote tumor progression by acting upon both cancerous and stromal cells." (PMID 25105093, 2014). "Heparanase is an endoglucuronidase that cleaves HS, and the expression levels of this enzyme correlate with the metastatic potential of tumor cells." (PMID 25187827, 2014).
tumor (continued). "A follow-up study revealed heparanase expression was increased in patients with metastasis and was dependent on tumor staging with expression levels lower in clinical TNM stages I and II than in III and IV." (PMID 25105093, 2014). "Taken together, heparanase, Sulf1, and Sulf2 are enzymes which appear, at least in pancreatic cancer, to be positive regulators of tumor development." (PMID 25105093, 2014). "Heparanase is an endoglycosidase enzyme present in activated leucocytes, mast cells, placental tissue, neutrophils and macrophages, and is involved in tumour metastasis and tissue invasion." (PMID 25295847, 2014). "High levels of HPSE mRNA and protein are expressed in most malignant tumors including HCC and are closely associated with tumor metastasis, angiogenesis and other diverse pathological and physiological processes." (PMID 25149140, 2014). "Statistical analysis confirmed that p16-positive tumours are more likely to express heparanase (two-sided Fisher's exact test; P = 0.027)." (PMID 24286246, 2014). "The remodeling of the ECM by heparanase is important for various physiological and pathological processes, including inflammation, wound healing, tumour angiogenesis and metastasis." (PMID 25295599, 2014). "A number of modified heparins and sulphated oligosaccharides have also been shown to be potent heparanase inhibitors with promising anti-tumour activities and have now advanced to the clinical testing stages." (PMID 25295847, 2014). "In contrast, the expression of heparanase is predominant in cancer samples with higher grades, whereas cytosines of CpG in these tumor tissues were almost low-methylated." (PMID 24632672, 2014). "PG545 is a synthetic, potent competitive inhibitor of heparanase demonstrated to possess significant anti-tumor, anti-angiogenic, and anti-metastatic activity in a variety of animal models." (PMID 25105093, 2014). "The clinical and the pathological data, together with the data of heparanase levels, were evaluated in a logistic regression model for tumor recurrence and survival." (PMID 24887057, 2014). "Heparanase, Sulf1, and Sulf2 drive a range of processes in the tumor microenvironment, many of which, in the case of heparanase and Sulf2 promote tumor malignancy, and some, in the case of Sulf1 inhibit malignancy." (PMID 25105093, 2014). "Further investigation of the underlying mechanism indicated that SDC-1 and FGF-2, but not FGFR-1, share a common transport route and co-localize with heparanase in the nucleus at mesenchymal tumor cells." (PMID 24551591, 2014). "Another mechanism, recently discovered, by which heparanase is able to promote tumor malignancy is via the stimulation of exosome secretion, although as yet Sulf1 and Sulf2 have not been shown to be involved in this process." (PMID 25105093, 2014). "For some time, the involvement of heparanase in the metastatic extravasation of tumor cells and invasion of immune cells has been known." (PMID 25105093, 2014). "Cleavage of heparan sulphate by heparanase leads to disassembly of extracellular barriers, enabling local invasion and metastatic spread of the tumour, and releases heparan sulphate-bound growth factors from the extracellular depots." (PMID 24286246, 2014). "The clinical significance of the enzyme in tumor progression emerged from a systematic evaluation of heparanase expression in primary human tumors." (PMID 24887057, 2014). "Increased expression of heparanase is detected in brain tumor glioma tissues from human and animal models, where heparanase is suggested to play an important role in the control of tumor cell proliferation and invasion." (PMID 25157361, 2014). "HPSE plays an important role in extravasation and invasion of tumor cells by cleaving heparan sulfate side chains of heparan sulfate proteoglycans on cell surfaces and in extracellular matrices of basement membrane." (PMID 25149140, 2014).